TNF (tumor necrosis factor)
Diseases named in the same sentence as TNF in open-access papers (continued):
Sharing a sentence is not in itself a finding about the gene and the disease.
rheumatoid arthritis (continued). "Supplementation of vitamin B6 was shown to suppress TNF-α and IL-6 levels in patients with rheumatoid arthritis." (PMID 37761018, 2023). "Anti-TNF treatment in rheumatic conditions, such as psoriatic arthritis and rheumatoid arthritis, has been found to modulate this pathway." (PMID 37809085, 2023). "Treatment with 20-hydroxyecdisone reduced TNF-α, IL-1β, IL-6 and NF-κB in rat serum in a rheumatoid arthritis model." (PMID 37687297, 2023). "The clinical course of rheumatoid arthritis has been transformed by targeted therapies, including those aimed at TNF, IL-6, B cells, T cell co-stimulation and the JAK–STAT pathway." (PMID 37938773, 2023). "TNF-alpha and IL-6 are key pathogens involved in immune-mediated bone diseases, such as postmenopausal osteoporosis and rheumatoid arthritis." (PMID 37246213, 2023). "The integration analyses also demonstrated that the inflammatory modules, such as cytokine-cytokine receptor interaction, TNF signaling pathway, and rheumatoid arthritis, were progressively enriched in the TAK-931-treated cells." (PMID 37980406, 2023). "Rheumatoid arthritis and the NF-κB, TNF, Toll-like receptor, IL-17, and NOD-like receptor signaling pathways were the most associated with the differentially expressed genes." (PMID 36756301, 2023). "These cytokines are already associated with diseases such as rheumatoid arthritis and psoriasis (TNF), Castleman disease and rheumatoid arthritis (IL-6), and type 2 diabetes, smoldering myeloma, urate crystal arthritis, and osteoarthritis among others (IL-1β)." (PMID 37112929, 2023). "The biological drug inhibiting tumor necrosis factor (TNFα) is an important treatment in a number of inflammatory conditions, including rheumatoid arthritis (RA), spondyloarthritis, psoriasis, hidradenitis suppurativa and inflammatory bowel disease (IBD)." (PMID 37047412, 2023). "In other systemic inflammatory diseases such as rheumatoid arthritis, pro-inflammatory cytokines in CSF have positively correlated with fatigue, and TNF blockade shown to reduce CSF protein levels." (PMID 36409402, 2023). "TNF-α, NF-, IL-1, and IL-6 are known key regulators in the pathogenesis of rheumatoid arthritis and other inflammatory diseases, and chloroquine has been shown to inhibit IL-1, IL-6, and TNF- production in human monocytes stimulated with lipopolysaccharide." (PMID 36677853, 2023). "Rheumatoid arthritis (RA) patients’ synovial cells express terminal-fucosylation but not core-fucosylation, and this expression correlates positively with tumor necrosis factor-alpha (TNFα)." (PMID 36980181, 2023). "TNF-α plays a significant role in the pathogenesis of several inflammatory diseases, such as arthritis, rheumatoid arthritis, ulcerative colitis, and Crohn’s disease." (PMID 37180165, 2023). "The idea of using the antagonists against TNF-α to block its cascade activities was initially converted into practice in 1994 for patients with rheumatoid arthritis." (PMID 37377731, 2023). "Three of the most essential aspects in the onset and regression of rheumatoid arthritis are TNF- α, IL-1 β, and IL-6." (PMID 37520245, 2023). "On the other hand, TNF-α-induced tissue destruction is deeply involved not only in periodontitis but also in the progression of rheumatoid arthritis." (PMID 36983482, 2023). "SHP-2 enhances the survival and invasion of fibroblast-like synoviocytes (FLS) and the responsiveness to platelet-derived growth factor (PDGF) and tumor necrosis factor (TNF) in rheumatoid arthritis through the activation of focal adhesion kinase (FAK)." (PMID 38060535, 2023). "The cellular inflammatory factors can also lead to rheumatoid arthritis, such as interleukin (IL)-17, tumor necrosis factor (TNF-α), IL-6, and IL-8." (PMID 36871051, 2023). "Anti-TNF-α treatment improves patient well-being before significant changes in tissue inflammation, in patients with rheumatoid arthritis." (PMID 36838809, 2023).
rheumatoid arthritis (continued). "TNF inhibitors appear to be the main contributors to immunogenicity because they are widely used, especially in rheumatoid arthritis." (PMID 37176711, 2023). "In rheumatoid arthritis (RA), cytokines such as TNF-α and IL-1 secreted by macrophages stimulate the differentiation of Th17 cells, which subsequently release IL-17 to induce RANKL production in synovial fibroblasts." (PMID 37492583, 2023). "More specifically, IL-34 is overexpressed in the inflamed synovium of rheumatoid arthritis patients, where it appears to act synergistic with TNF and IL-1β, inducing osteoclastogenesis and contributing to tissue inflammation and bone erosion." (PMID 35347503, 2023). "Some randomized controlled and observational studies for the withdrawal of tumor necrosis factor inhibitors (TNFi) in rheumatoid arthritis have been conducted, suggesting that tapering is feasible." (PMID 37415053, 2023). "The mean duration of TNF-a antagonist exposure has varied widely, from 7 to 123 months in rheumatoid arthritis and 1 to 180 months in Crohn’s disease." (PMID 37250639, 2023). "The IL-17 signaling pathway, the TNF signaling pathway, viral protein interaction with cytokine and cytokine receptor, rheumatoid arthritis, and Staphylococcus aureus infection were found to be the top five enriched KEGG pathways." (PMID 36792688, 2023). "We present the case of an M. marinum infection in a patient who presented with chronic skin and soft tissue lesions and who had received an anti-tumor necrosis factor alpha (anti-TNF-a) drug following a diagnosis of rheumatoid arthritis." (PMID 37512971, 2023). "In rheumatoid arthritis (RA) patients, continuous release of TNF-α in the joint space can sustain tissue inflammation and, thus, leads to bone and cartilage impairment." (PMID 37047115, 2023). "The current indications for anti-TNF-α include immune-mediated inflammatory diseases (IMID) such as rheumatoid arthritis, Crohn's disease, juvenile idiopathic arthritis, plaque psoriasis, ankylosing spondylitis, ulcerative colitis, and non-infectious uveitis." (PMID 37534280, 2023). "The reason for TNF-a antagonist therapy was usually rheumatoid arthritis, although some patients had ankylosing arthritis, Crohn’s disease, or even sarcoidosis." (PMID 37250639, 2023). "Conclusion: 4-(1-hydroxy-3-oxo-1H-isoindol-2-yl) benzoic acid (PubChemID 18873897), have the potential to be a good small molecule inhibitor of TNF-α against rheumatoid arthritis." (PMID 36825150, 2023). "Conventional (such as methotrexate and sulfasalazine) and biological (TNF and IL-6 inhibitors) DMARDs have been the mainstay for treating patients with rheumatoid arthritis." (PMID 37373437, 2023). "The KEGG result manifested that DEGs were found to be mostly related to IL-17 signaling pathway, TNF signaling pathway oxytocin signaling pathway, rheumatoid arthritis, NF-kappa B signaling pathway, FOXO signaling pathway and so on." (PMID 36781858, 2023). "Myocardial infarction rates are reduced in rheumatoid arthritis patients taking anti-TNF-α therapies." (PMID 37534280, 2023). "Adalimumab, which is an anti-human tumor necrosis factor (TNF)-α antibody prescribed for the treatment of rheumatoid arthritis, psoriatic arthritis, Crohn’s disease, and other auto-immune diseases, is known to elicit ADA responses in 23% of patients." (PMID 37759665, 2023). "Side effects from using TNF-α inhibitors have been observed in individuals with rheumatoid arthritis and include potential cancer risks, however, the study results remain controversial." (PMID 38137108, 2023). "For instance, in the case of rheumatoid arthritis (RA), miR-146 was observed to be overexpressed in synovial tissue following stimulation with inflammatory cytokines tumor necrosis factor-alpha (TNF-α) and interleukin-1β (IL-1β)." (PMID 37685951, 2023). "As an example, adalimumab, a fully human anti-TNFα antibody, generates ADAs in 25 to 30% of patients suffering from rheumatoid arthritis." (PMID 37575221, 2023).
rheumatoid arthritis (continued). "Etanercept, a soluble fusion protein that binds TNF-α, has been proved to be an effective choice targeting several inflammatory diseases, especially rheumatoid arthritis." (PMID 36845391, 2023). "This notion is synonymous with how single-agent biologics, such as TNF-α antagonists, are thought to ameliorate the progression of autoimmune disorders in vivo (e.g., rheumatoid arthritis or Crohn’s disease) characterized by complex inflammatory networks." (PMID 37092550, 2023). "Treatment with ozoralizumab has been shown to provide beneficial effects in the treatment of rheumatoid arthritis (RA) comparable to those obtained with other TNFα inhibitors." (PMID 37122706, 2023). "For example, TNF-α inhibitors have been approved for the treatment of inflammatory bowel disease, rheumatoid arthritis, and ankylosing spondylitis." (PMID 36837593, 2023). "Treatment with PTGS2 has been shown to reduce inflammation in rheumatoid arthritis rats by reducing serum levels of interleukin 1β, interleukin six and tumor necrosis factor α and their mRNA expression." (PMID 36923645, 2023). "This was driven primarily by findings from the postmarketing study of tofacitinib versus tumor necrosis factor (TNF) blockers in rheumatoid arthritis." (PMID 37501130, 2023). "Metformin has been shown to inhibit expression of IL-6 and TNF-α in HaCaT keratinocytes, and to reduce IL-6 and IL-8 in rheumatoid arthritis synovial explants." (PMID 37108132, 2023). "Infliximab and Etanercept (TNF-α inhibitors) and Tocilizumab (IL-6 inhibitor) are currently prescribed to treat rheumatoid arthritis." (PMID 37108210, 2023). "Therefore, to assess whether the defect in LXR signalling is because of a failure of oxysterol production or signalling, we performed lipidomics on BMDMs treated with a cocktail of inflammatory cytokines associated with rheumatoid arthritis (TNF, GM‐CSF, IL‐1β and IL‐6)." (PMID 37091327, 2023). "LXA4 inhibited synoviocyte proliferation and also decreased the levels of IL-6, IL-1β, and TNF-α in rheumatoid arthritis." (PMID 37388729, 2023). "KEGG analysis showed that these genes play a major role in the IL-17 signaling pathway, the TNF signaling pathway, and rheumatoid arthritis." (PMID 36792688, 2023). "Rheumatoid arthritis (RA) is an autoimmune inflammatory disease associated with rheumatoid factors and anti-cyclocitrullinate peptide antibodies, which involve inflammatory cytokines, such as TNFα, IL-1, and IL-6." (PMID 36518035, 2023). "Avascular areas were found in 20.6% of the subjects with rheumatoid arthritis at baseline and in 0% of the patients after 12 months of anti-TNF-alpha treatment." (PMID 37370974, 2023). "NG-R1 was shown to alleviate rheumatoid arthritis in TNF-tg mice by inhibiting the TNF-α signaling pathway to promote lymphatic drainage function." (PMID 36713827, 2023). "Elderly rheumatoid arthritis patients showed improved cognitive performance with subcutaneous anti-TNF-α therapy using drugs like etanercept and adalimumab." (PMID 38201258, 2023). "TNFα and IL-1ß are major pro-inflammatory cytokines in inflammatory joint diseases, including rheumatoid arthritis and osteoarthritis, and are discussed as potential diagnostic markers for disease progression." (PMID 37564645, 2023). "The inhibitors of TNF-α can be used to treat inflammatory diseases, including inflammatory bowel disease and rheumatoid arthritis." (PMID 36845140, 2023). "Several studies have reported that IL-17 and TNF-α additively or synergistically induce the expression of many genes to promote the development of various diseases, such as psoriasis and rheumatoid arthritis." (PMID 35844613, 2022). "Meanwhile, TNF-α, by and large, contributes to the progressions of many inflammatory diseases like rheumatoid arthritis and OA." (PMID 35937393, 2022).
rheumatoid arthritis (continued). "Certolizumab pegol (CZP) is a PEGylated Fc-free tumor necrosis factor (TNF) inhibitor antibody approved for use in the treatment of rheumatoid arthritis (RA), Crohn’s disease, psoriatic arthritis, axial spondyloarthritis and psoriasis." (PMID 35413058, 2022). "TNF-α is a master pro-inflammatory cytokine and plays a major pathological role in corticosteroid resistant asthma, inflammatory bowel disease, psoriasis, rheumatoid arthritis and COVID-19 cytokine storm among others." (PMID 36793921, 2022). "In the present study, pristimerin treatment led to a dose-dependent decrease in cell viability and migration in TNF-α stimulated human rheumatoid arthritis fibroblast-like synoviocytes MH7A." (PMID 36144243, 2022). "In the clinic, rhTNFR:Fc is used to neutralize TNF-α to alleviate the aberrant proinflammatory response during the pathogenesis of rheumatoid arthritis, ankylosing spondylitis, psoriasis, and Crohn’s disease." (PMID 35013173, 2022). "A retrospective cohort study was conducted in Prince Mohammad bin Abdulaziz Hospital for all patients aged ≥ 18-year-old diagnosed with seropositive rheumatoid arthritis and started on TNF inhibitors or non-TNF biologics in outpatient clinics since 2015." (PMID 35784983, 2022). "TNF-α also increased DKK1 secretion from synoviocytes in rheumatoid arthritis, which upregulates MKK3-p38 and inhibits the canonical Wnt-signaling pathway." (PMID 35160258, 2022). "TNF- α was considered as the crucial factor in the pathogenesisof many autoimmune and inflammatory diseases, such as Systemic Lupus Erythematosus, Rheumatoid Arthritis and Psoriasis." (PMID 36518124, 2022). "The success of TNF-inhibitors in the treatment of psoriasis, rheumatoid arthritis and pyoderma gangrenosum is well-known, but the positive effects in VLUs have only been reported in case series." (PMID 35742965, 2022). "We investigated B-cell-activating factor (BAFF) in relation to response to treatment with TNF inhibitors (TNFis) in rheumatoid arthritis (RA)." (PMID 36079136, 2022). "Such resistance development occurs with the commonly used tumor necrosis-alpha (TNFα) inhibitors for rheumatoid arthritis, which also have unpleasant side effects, and novel approaches with selective inducers of immune tolerance are under investigation." (PMID 35216184, 2022). "in the TNF‐transgenic (TNF‐Tg) rheumatoid arthritis mouse model has purified the CD19+ B cells from bone marrow (TNF‐Tg BM) or subchondral bone marrow (TNF‐Tg SBM) and compared their transcriptome profiles between the cell groups." (PMID 36305631, 2022). "Around 30% of rheumatoid arthritis patients withdraw from treatment with a TNF-blocking agent for these reasons in the first year of therapy." (PMID 35844585, 2022). "Enrichment analysis showed that most of the enriched genes were primarily involved in the TNF signaling pathway via NFκB, IL-17 signaling pathway, and rheumatoid arthritis pathways." (PMID 36439145, 2022). "Adalimumab is a subcutaneously administered biological disease modifier for the treatment of rheumatoid arthritis and other chronic debilitating diseases mediated by tumor necrosis factor." (PMID 35356949, 2022). "Comparison of the expression of RAGE mRNA, TNF-α, and IL-1β in synovial tissue of patients with rheumatoid arthritis and osteoarthritis revealed that the concentration of TNF-α and IL-1β in synovial tissue of the former was higher than that of the latter." (PMID 35956875, 2022). "For instance, TNF inhibitors, both antibody- and receptor-Ig–based biologics, have strong disease-attenuating efficacy in rheumatoid arthritis (RA), psoriasis, and IBD, with a clinical response limited to 30–40% of subjects." (PMID 35604387, 2022). "Remarkably, SA removal induced a clear activated phenotype in SFs, including enriched pathways for Rheumatoid Arthritis, cytokine signaling (TNFα, IL-17, chemokines) and NFkB and TLR signalling." (PMID 35371069, 2022).
rheumatoid arthritis (continued). "We present a female patient with EM with characteristic skin lesions following anti-TNF-α medication adalimumab for rheumatoid arthritis." (PMID 35036238, 2022). "TNF inhibitors have been successfully developed and applied in the clinical treatment of autoimmune diseases such as Crohn’s disease and rheumatoid arthritis." (PMID 36544491, 2022). "For example, IL-17 upregulated TNF receptor II (TNFR-II) expression in synoviocytes and acted together with TNF to contribute rheumatoid arthritis." (PMID 36118416, 2022). "This led to a prospective safety trial comparing tofacitinib with TNF inhibitors, the Oral Rheumatoid Arthritis Trial (ORAL) Surveillance." (PMID 36352850, 2022). "For instance, Takinib, a TAK1-specific inhibitor, was reported to mediate cell death in rheumatoid arthritis and breast cancer by suppressing TNF-α production." (PMID 35409346, 2022). "KEGG pathway analysis showed that DEGs were increased in the cytokine–cytokine receptor interaction, TNF signaling pathway, NF-κB signaling pathway, and rheumatoid arthritis." (PMID 36678502, 2022). "A retrospective multicenter study analyzed data of all adult patients with rheumatoid arthritis (n = 3032) starting TNF inhibitor as the first-line biological therapy in combination with csDMARDs or in monotherapy from January 1st 2012 to December 31st 2020." (PMID 35338383, 2022). "The role of TNF-α in autoimmune diseases (rheumatoid arthritis, psoriasis, inflammatory bowel disease) is well-described, while it has dual function in cancer development." (PMID 36555579, 2022). "Wang and Guo (2021) studied the effects of TNF – α on the autophagy and NF – kappaB signaling pathway of fibroblast like synoviocytes in rheumatoid arthritis." (PMID 35232381, 2022). "Among immunomodulators, TNF inhibitors are widely used as treatment for a variety of conditions involving hyperactive immune disorders such as rheumatoid arthritis, psoriasis, and inflammatory bowel disease (IBD)." (PMID 36159650, 2022). "The drug infliximab, a neutralizing antibody to TNF‐α used in the treatment of rheumatoid arthritis among other autoimmune diseases, has been evaluated for its effect against periodontal disease in both animals and humans." (PMID 34626163, 2022). "In the collagen-induced rheumatoid arthritis model, CD200Fc treatment significantly lowers expression of pro-inflammatory cytokines (IL-1β and TNFα) and lowers disease severity at 10 days post disease induction." (PMID 35359946, 2022). "TNF-α is involved in a variety of autoimmune diseases including psoriasis, inflammatory bowel disease, rheumatoid arthritis, systemic sclerosis, systemic lupus erythematosus, multiple sclerosis, diabetes, and ankylosing spondylitis." (PMID 36574379, 2022). "The role of LRG1 as a pro-inflammatory mediator is more clearly established in the pathogenesis of rheumatoid arthritis (RA), where high levels of Th17 cells and Th17-related cytokines, including TNFα and IL-6, cause severe joint destruction and correlate with poor prognosis." (PMID 35062948, 2022). "Two of the metalloprotease inhibitors tested in our study, DPC‐333 and apratastat, were developed to block ADAM17‐mediated TNFα shedding and previously entered phase 2 clinical trials for the treatment of the inflammatory joint disorder rheumatoid arthritis." (PMID 35527514, 2022). "Followed by chemokine signaling pathway, TNF signaling pathway, cancer pathway, IL-17 signaling pathway, rheumatoid arthritis, drug metabolism-cytochrome P450, inflammatory bowel disease (IBD) and cell adhesion molecule (CAM) enriched in signaling pathways." (PMID 36313318, 2022). "TNF-α has been reported to induce the expression of VEGF in the synovial fluid of patients with rheumatoid arthritis." (PMID 35028065, 2022). "KEGG pathway analysis indicated that the DEGs were significantly enriched in IL-17 signaling pathway, Rheumatoid arthritis, TNF signaling pathway and Cytokine-cytokine receptor interaction." (PMID 36118873, 2022).